HPX (hemopexin)
Diseases named in the same sentence as HPX in open-access papers (continued):
Sharing a sentence is not in itself a finding about the gene and the disease.
malaria (continued). "To determine whether the HP/HB and/or HPX/heme scavenging systems are protective against malaria we combined the analyzes of a pediatric P. falciparum malaria case-control study with experimental models of malaria in mice carrying Hp and/or Hpx genetic deletions." (PMID 38307624, 2024). "Moreover, the age-dependent renal transcriptional response and protective effect of HP and HPX in Plasmodium-infected mice supports the idea of an age-dependent impairment of tissue damage control mechanisms establishing disease tolerance to malaria." (PMID 38307624, 2024). "To probe the pathologic effect of labile heme in P. falciparum malaria we asked whether targeting extracellular HB and/or labile heme by HP and HPX, respectively, limit the accumulation of labile heme and/or prevent the pathogenesis of severe presentations of malaria." (PMID 38307624, 2024). "In this respect, it is tempting to speculate that hemopexin depletion in the human host may further enhance the impact of HE on parasitemia, and thus may explain the disparity between severe malaria defined by parasitemias of ≈ 20% in mice versus ≥ 0.5% in man." (PMID 26465787, 2015). "The age-dependent protective effect of HP and/or HPX against malaria AKI in mice and the inverse correlation of HPX and heme with renal impairment in P. falciparum malaria are consistent with the age-dependent increase in susceptibility to renal impairment in P. falciparum malaria." (PMID 38307624, 2024). "This was also the case for Hp−/−Hpx−/−Hmox1+/− mice, lacking one Hmox1 allele, suggesting that the extent of renal iron overload imposed by HP and HPX depletion is not sufficient to precipitate the pathogenesis of malaria AKI in adult mice." (PMID 38307624, 2024). "This suggests that, in contrast to other components of the heme/iron detoxifying pathway, including HO-1, ferritin H chain or ferroportin 1, HP and HPX are not essential to survive malaria in adult mice." (PMID 38307624, 2024). "We found that labile heme is an independent risk factor for cerebral and non-cerebral presentations of severe P. falciparum malaria and that HP and HPX act in an age-depended manner to prevent the pathogenesis of non-cerebral severe malaria in mice." (PMID 38307624, 2024). "Here, we tested whether scavenging of extracellular HB and/or labile heme, by haptoglobin (HP) and/or hemopexin (HPX), respectively, counter the pathogenesis of severe presentations of malaria." (PMID 38307624, 2024). "In contrast, severe non-cerebral malaria was associated with lower concentration of circulating HP, but not HPX, compared with uncomplicated malaria." (PMID 38307624, 2024). "The concentrations of HP and HPX in serum were indistinguishable in children that developed P. falciparum CM versus those with uncomplicated malaria." (PMID 38307624, 2024). "In addition, the significant multivariate correlation of EPO, hemopexin and total heme with TNF-α, IL-10, IP-10 and MCP-1 suggests the implication of EPO in the complex network of factors of the immune system influenced by heme during severe malaria." (PMID 27441662, 2016).
hepatocellular carcinoma (10 papers, 2012 to 2025). A malignant tumor that arises from hepatocytes. "We have identified candidate HPX receptors and human proteins that bind to heme–HPX, i.e., HPX “interactomes,” in a human neutrophil model (promyelocytic HL-60 cells), in hepatoma HepG2 cells, and in primary human hepatocytes." (PMID 41384245, 2025). "The selected examples are diminished haptoglobin values in hepatocellular carcinoma, reduced hemopexin levels in prostate cancer patients, and downregulated ceruloplasmin in adrenocortical and hepatocellular carcinomas." (PMID 38201509, 2023). "In that study, heme-HPX complexes were as effective as diferric-transferrin as a sole source of iron for the growth of mouse hepatoma cells that were used as models of liver parenchymal cells (i.e., hepatocytes)." (PMID 31554244, 2019). "In relation to cancer, hemopexin was reported to be upregulated in pleural effusions of lung-cancer patients and in plasma of pancreatic-cancer patients before resection, and the fucosylated form of hemopexin was reported as an accurate serum marker for hepatocellular carcinoma." (PMID 32663208, 2020). "Hemopexin is expressed in a model of hepatocellular carcinoma from hepatitis B in woodchucks." (PMID 30598658, 2018). "As previously reviewed, comparison of the extent of exogenous heme clearance with HPX levels supported that HPX recycles after heme delivery to the liver, which was subsequently shown directly using radioactive heme-125I-HPX in rats and confirmed in human hepatoma cells." (PMID 26175690, 2015). "Recent studies have shown that the changes in the patterns of glycosylation on hemopexin and clusterin may be useful for the diagnosis for hepatocellular carcinoma." (PMID 22672759, 2012). "All of these provide strong evidence that APOC3, APOH, HPX, and FGB can be used as biomarkers for hepatocellular carcinoma." (PMID 35449866, 2022). "Previous studies have shown the nuclear translocation of HO-1 in human prostate cancer cells, murine fibroblasts and mouse hepatoma cells exposed to strong oxidant conditions, such as cigarette smoke or hypoxia or hemin with or without hemopexin." (PMID 26779023, 2015). "Maximum HO1 protein levels (~2-fold) are induced in mouse hepatoma cells within 3–6 h exposure to heme-HPX, whereas the iron released from heme catabolism may not induce ferritin via translation until ~7–11 h." (PMID 26175690, 2015).
breast carcinoma (9 papers, 2006 to 2025). "Increased hemopexin levels have been found in patients with diabetes mellitus and are associated with some malignancies, such as malignant melanoma and breast cancer." (PMID 23039107, 2012). "Hemopexin, a protein involved in matrix metalloproteinase (MMPs) activation, has been linked to invasion and metastasis in many cancer model systems, including human breast cancer." (PMID 16542425, 2006). "We have also characterized the molecular profile of PNI-competent breast cancer cells and showed that CPLANE1 and hemopexin are potential markers for PNI-competent breast cancer cells." (PMID 40628700, 2025). "Other risk factors, such as HPX and GRIA3, have been reported in many cancers, including glioma, breast cancer and pancreatic cancer." (PMID 31907037, 2020). "Hemopexin (HPX), which acts as a scavenger of toxic plasma heme and a transporter of it to the liver, has been demonstrated to be closely associated to the occurrence and development of breast cancer." (PMID 35449866, 2022). "Furthermore, HPX was overexpressed during other malignancies, like breast cancer or colorectal cancer." (PMID 30065196, 2018). "Interestingly, we observed induction of hemopexin in PNI-competent breast cancer cells." (PMID 40628700, 2025).
hemolysis (9 papers, 2010 to 2025). Disruption of the integrity of the erythrocyte membrane causing release of hemoglobin. "Hemopexin, similarly to haptoglobin, is sensitive to intravascular hemolysis, as it binds free heme, which is released after hemoglobin degradation." (PMID 40429487, 2025). "The intravascular hemolysis was reduced in P1 and (particularly) P2, as shown by a decrease in plasma levels of hemoglobin and heme (both of which were abnormally high before GT) and an increase in plasma hemopexin." (PMID 40169559, 2025). "In situations of ongoing chronic hemolysis (e.g. SCD), when the binding capacity of haptoglobin and hemopexin is saturated, free heme and free hemoglobin are delivered to the kidney." (PMID 26406992, 2015). "In our study, the incidence of hemolysis was significantly higher among patients on ECMO compared to those without ECMO (81% vs. 22%), with significant depletion in the markers haptoglobin and hemopexin throughout the whole study." (PMID 40429487, 2025). "Plasma HPX levels are depleted in SCD patients and mice because of chronic intravascular hemolysis." (PMID 33841413, 2021). "The proinfammatory vasculotoxic effects of intravascular hemolysis are modulated by plasma hemoglobin and heme clearance via the haptoglobin/CD163 system and the hemopexin/CD91 system, respectively, and detoxification through the heme oxygenase/ferritin system." (PMID 25506596, 2013). "Additionally, intravascular hemolysis (IVH) was quantified using several indirect markers (LDH, α-HBDH, haptoglobin and hemopexin), which all showed elevated IVH in SMA." (PMID 20386613, 2010).
liver fibrosis (8 papers, 2012 to 2025). "This feature has led to the belief that hemopexin prevents the body from heme-catalyzed oxidation as well as heme-bound iron loss, thus protecting against inflammation and liver fibrosis." (PMID 27230648, 2016). "In this study, we developed a mLC-MS/MS-PRM assay for the quantification of site-specific mucin-type O-glycoforms of hemopexin, which we previously reported as a promising candidate biomarker for the serologic monitoring of liver fibrosis." (PMID 35408612, 2022). "In earlier studies, we reported that nLC-MS/MS measurement of the O-glycoforms of HPX is an indicator of liver fibrosis." (PMID 35408612, 2022). "The application of this assay to patients with hepatitis C virus (HCV)-induced liver fibrosis demonstrated that specific IgG and HPX glycoforms could effectively detect fibrotic disease at varying stages." (PMID 40519814, 2025). "In addition, decrease of of HPX level was also observed in rat model of liver fibrosis induced by carbon tetrachloride (CCl4)." (PMID 29270132, 2017). "Hemolytic stress in haptoglobin-hemopexin double-null mice, but not single knock-out mice, causes pronounced fibrosis suggesting that both haptoglobin and hemopexin, which was also identified in this study, are important for protection from liver fibrosis." (PMID 22761838, 2012).
Obesity (8 papers, 2019 to 2026). Accumulation of substantial excess body fat. "Similarly, an increase in heme protein hemopexin (HPX) and cuproprotein ceruloplasmin (CP) levels has been associated with increased triglyceride levels and obesity, respectively." (PMID 34066295, 2021). "LRG1 and HPX were among the twenty-three up-regulated proteins in the generational obesity comparison group." (PMID 39339686, 2024). "Suppressing the expression and function of either LRG1 or HPX presents a promising strategy for combating obesity and obesity-related metabolic diseases." (PMID 39339686, 2024). "The role of HPX in obesity is unclear, but it has been shown to be expressed by the adipose tissue and implicated in lipid metabolism." (PMID 32709962, 2020). "The following seven proteins are present in higher amounts in the Obesity group compared with the Control group: hemopexin—HPX, complement factor B—CFB, complement C3—C3, kininogen-1—KNG1, vitronectin—VTN, pigment epithelium-derived factor—SERPINF1 and beta-Ala-His dipeptidase—CNDP1." (PMID 41441338, 2025). "Interestingly, high levels of CRP are positively correlated with an increase in LRG1 and HPX, suggesting the potential interplay between these proteins in the context of obesity." (PMID 39339686, 2024). "Compared to controls, immune‐related pathways such as adaptive immunity and leukocyte‐mediated processes (e.g., STX7, HPX, LAMP1, C5) were upregulated in obesity." (PMID 41077621, 2026). "In this study, HFHS-induced obesity alone decreased both superoxide dismutase 2 (SOD2) and hemopexin (HPX1)." (PMID 39910959, 2025).
COVID-19 (7 papers, 2021 to 2025). A disease caused by infection with severe acute respiratory syndrome coronavirus 2. "In CD3+ lymphocytes from COVID-19 patients, protein–protein interactions (PPIs) between HPX, Tf, HFE, and Cp were associated with high confidence (0.7)." (PMID 36613462, 2022). "HPX is a heme scavenger protein that increases with age, is significantly elevated in both Cov and nLongC compared to controls, and has been associated with COVID-19 severity." (PMID 41369364, 2025). "Age, Sex, Days since diagnosis, or Symptoms had no significant bias with respect to their distribution across healthy controls and COVID-19 convalescents, with the exception of one protein (HPX) (adjusted p-value > 0.20)." (PMID 38396092, 2024). "Our results reported increased HPX levels in COVID-19 and long-COVID patients; this protein is known to protect cells from free heme toxicity occurring during hemolysis." (PMID 36613462, 2022). "Regarding the COVID-19 group, we observed an increasing trend in patients compared to the healthy controls that was found to be significant for Cp, Tf, HPX, and LCN2." (PMID 36613462, 2022). "Levels of hemoglobin and heme-scavenging proteins (i.e., hemopexin, albumin) were often changed in COVID-19 patients." (PMID 33925394, 2021). "In line with this theory, in our cohort of long-COVID patients, we found a decreasing trend of antioxidant proteins, such as Cp, Tf, and SOD1, in comparison to COVID-19 patients and healthy controls, and a significant increase in HPX levels compared to the healthy controls." (PMID 36613462, 2022). "Finally, we observed upregulation of markers of hemolysis (haptoglobin [Hb scavenger] and hemopexin [heme scavenger]), which have been reported to be heightened in COVID-19 infected human patients." (PMID 36614003, 2022). "In contrast, there is evidence for higher levels of hemopexin and haptoglobin in COVID-19 patients." (PMID 33925394, 2021). "HPX has an anti-inflammatory effect by clearing hemolysis-related degradation products that induce inflammation and oxidative stress as well as acting as an inhibitor of hemolysis-induced complement activation and therefore has been proposed as a therapeutic agent in COVID-19." (PMID 40773458, 2025). "Plasma proteins including AAT, ABO, APP, FGA, HPX, ITIH4, PON and others showed similar or higher observation frequency in NHP compared to COVID-19." (PMID 37031181, 2023). "We found that the amounts of Cp, Tf, HPX, LCN2, and SOD1 increased in PBMCs isolated from COVID-19 patients, compared to both the long-COVID group and the control group." (PMID 36613462, 2022).
atherosclerosis (6 papers, 2012 to 2024). A disease characterized by the build-up of fatty material and calcium deposition in the arterial wall resulting in partial or complete occlusion of the arterial lumen. "Hemopexin is a heme scavenging protein considered to be generally protective against cardiovascular disease and atherosclerosis." (PMID 38825704, 2024). "Given its protective function against heme toxicity in hemolysis and concurrent inflammation, HPX has been investigated as a potential biomarker and therapeutic agent in heme-related pathologies and atherosclerosis." (PMID 38022615, 2023). "Particularly, by removing heme in atherosclerosis, HPX has been demonstrated to suppress the secretion of proinflammatory cytokines from macrophages, thereby illustrating a protective function for high-density lipoprotein (HDL) in the serum." (PMID 33672727, 2021). "That VPO1 in aorta is stimulated by LPS or TNF-α sheds light on the studies of hPx enzymes and atherosclerosis." (PMID 27167346, 2016). "Our data suggest that VPO1 may be a novel mediator of atherosclerosis, opening a new avenue to study hPx enzymes and atherosclerosis." (PMID 27167346, 2016). "Their plasma revealed downregulation of certain cardiovascular-protective proteins such as apolipoprotein A-IV, haptoglobin, and hemopexin, which could explain the accelerated atherosclerosis process accompanying HD." (PMID 22792249, 2012).
Cerebral ischemia (6 papers, 2013 to 2024). Restriction of arterial blood supply to the brain associated with insufficient oxygenation to support the metabolic requirements of the tissue. "Interestingly, elevated HPX levels in the CSF after SAH were associated with a higher likelihood of delayed cerebral ischemia and poorer neurological outcomes, which differed from the effects of HPX in other diseases." (PMID 38022615, 2023). "Interestingly, hemopexin injection is neuroprotective in cerebral ischemia model and hemopexin knockout mice are more susceptible to neuronal injury after intracerebral bleeding." (PMID 30011792, 2018). "Taken together, these data provide novel evidence for the protective role of HPX in improvement of cognitive impairment after cerebral ischemia injury." (PMID 30646866, 2019). "HPX can promote angiogenesis in rats via up-regulating HO-1 after cerebral ischemia-reperfusion injury." (PMID 29298658, 2018). "Our previous study showed that HPX expression increased in the vascular system after cerebral ischemia, and the intracerebroventricular injection of HPX showed a dose dependence reduce in the cerebral infarction volume of rats after I/R." (PMID 29298658, 2018). "Our results were consistent with previous studies that reported HPX could alleviate cognitive dysfunction after focal cerebral ischemia–reperfusion injury in rats." (PMID 38183122, 2024). "In present study we found that in comparison to the physiological conditions, the expression of HPX protein was significantly increased after cerebral ischemia, mainly in neurons and also in a small amount of astrocytes located in the subendothelial layer of the vessels." (PMID 23758755, 2013). "This study found that HPX-null mice were more vulnerable to oxidative stress during cerebral ischemia injury than their wild-type counterparts, an observation which was consistent with a recent study in cultured neuronal cells, which showed that HPX decreased heme accumulation and catabolism." (PMID 23758755, 2013). "In their study they also found that the mRNA level of HPX was not increased after cerebral ischemia-reperfusion." (PMID 23758755, 2013). "However, the expression of HPX in the brain was not well elucidated and its expression after cerebral ischemia-reperfusion injury was also poorly studied." (PMID 23758755, 2013). "Surprisingly, HPX was reported to be locally expressed in the central nervous system (CNS), but reports on its cellular localization in CNS are contradictory and the temporal changes of its expression after cerebral ischemia has not be observed." (PMID 23758755, 2013).
Cirrhosis (6 papers, 2013 to 2025). A chronic disorder of the liver in which liver tissue becomes scarred and is partially replaced by regenerative nodules and fibrotic tissue resulting in loss of liver function. "For example, the fucosylated intensities of the tri-antennary glycoform of the SWPAVGNCSSALR peptide of hemopexin increase in cirrhosis consistently 2- to fivefold while the intensities of the bi-antennary glycoforms increase 1- to threefold." (PMID 34857845, 2021). "Label free LC-MS/MS proteomic analysis resulted in the identification of two non-invasive independent circulating proteins, SIPA1L1 and hemopexin, biomarkers of fibrosis and cirrhosis, respectively." (PMID 27230648, 2016). "Despite hemopexin failing to demonstrate its value as an indicator of cirrhosis, SIPA1L1 showed a clear serum diminution and a great accuracy at identifying early fibrotic stages in the validation group." (PMID 27230648, 2016). "HPX levels in subject plasma showed an overall trend of lowered expression in those with active cirrhosis compared to controls, with a “bounce back” effect seen as the protein levels are somewhat restored to control levels in the HCC subjects." (PMID 23935864, 2013). "In particular, SIPA1L1 was down expressed in fibrosis whereas hemopexin was increased in cirrhosis." (PMID 27230648, 2016). "The results show an approximately fourfold increase in disialylated O-glycopeptide of HPX in cirrhosis and further increase in the cirrhotics with HCC with a simultaneous approximately 20 % decrease in the monosialylated O-glycopeptide of HPX." (PMID 27688741, 2016). "We observe lower intensities in the non-fucosylated glycopeptides of proteins (hemopexin, clusterin, ITIH4, fibrinogen) reported to decrease in cirrhosis while the non-fucosylated glycopeptide of alpha-2 macroglobulin has higher intensity in cirrhosis in line with its increased serum concentration." (PMID 34857845, 2021).